C3 (complement C3)
Diseases named in the same sentence as C3 in open-access papers (continued):
Sharing a sentence is not in itself a finding about the gene and the disease.
steatosis (9 papers, 2009 to 2025). Increased lipid within the cytoplasm of cells. "In the AFLD animal model, activated the complement components were deposited in the liver, and C3-deficient animals tend to reduce fatty infiltration and steatosis after ethanol-induced liver damage, implying that a low level of C3 is beneficial to fatty deposits in liver." (PMID 25856141, 2015). "In view of the accumulation of C3 activation products and properdin around steatotic hepatocytes that we observed, we investigated the potential association between hepatic C3c and properdin levels and the presence of steatosis." (PMID 25299043, 2014). "The results of univariate analysis showed IgA, C3, and ALT might be the risk factors for steatosis (>33%), ANA and C3 might be the risk factors for ballooning, and ANA, IgA, and C3 may be the risk factors for NAS (≥5)." (PMID 40422243, 2025). "Further studies are required to characterize IgG, C3, and NETs in a MASLD-only cohort and explore whether IgG–C3 interactions during steatosis prime the liver for subsequent NETs-driven injury in MASH." (PMID 40422243, 2025). "We had shown high core expression leads to bland steatosis and C3 downregulation (experiment I), in contrast to the findings in experiments II and III, suggesting that C3 is a critical determinant of hepatic inflammation in the HCV core-expressing liver." (PMID 19664232, 2009).
Crohn disease (8 papers, 2015 to 2023). A gastrointestinal disorder characterized by chronic inflammation involving all layers of the intestinal wall, noncaseating granulomas affecting the intestinal wall and regional lymph nodes, and transmural fibrosis. "Serum C3 and C4 complement components were increased in human patients with Crohn's disease, with higher levels found in human patients with active disease compared to inactive disease." (PMID 37279179, 2023). "Both C3 and C4 transcripts have been observed in the small intestinal crypts in biopsies from both healthy patients and patients with Crohn's disease, and C3 was present in the cultured intestinal tissue from healthy individuals." (PMID 34806406, 2022). "The small intestinal crypts in Crohn’s disease (CD) patients show a significant alteration in the level of C3 and C4 mRNA, while the intestinal mucus of IBD patients exhibits upregulated levels of C3 mRNA." (PMID 34349661, 2021). "In another report that measured complement in lumen samples, higher C3 and C4 levels were found in jejunal secretions from Crohn’s disease patients compared to healthy participants." (PMID 25688244, 2015). "Otherwise multiple reports identify epithelial cells as a source, for example, C4 mRNA was detected in both healthy participants’ and Crohn’s disease patients’ mucosa while C3 expression was limited to crypt cells in inflamed samples." (PMID 25688244, 2015). "Similarly, a recent study observed upregulation of C3, but not C5 expression in both inflamed and noninflamed (remission) biopsies from patients with Crohn's disease compared with healthy controls." (PMID 34806406, 2022).
hemolytic-uremic syndrome (8 papers, 2013 to 2024). Acute kidney injury associated with microangiopathic hemolytic anemia and thrombocytopenia. "As an example, patients diagnosed with atypical Hemolytic Uremic Syndrome and with a positive genetic report identifying pathogenic variants in CFH, C3 or CFB genes, are at moderate to high risk of recurrence after transplantation." (PMID 36782285, 2023). "In thrombotic microangiopathy, glomerulopathy is triggered by the activation of the coagulation cascade in renal tissue due to the presence of antiendothelial antibodies, C3 and/or C4 components, resulting in morphological changes similar to those found in TG and hemolytic-uremic syndrome (HUS)." (PMID 23935649, 2013).
Huntington disease (8 papers, 2019 to 2026). Huntington disease (HD) is a rare neurodegenerative disorder of the central nervous system characterized by unwanted choreatic movements, behavioral and psychiatric disturbances and dementia. "The authors choose C3 as a marker for A1 astrocytes and identified C3-positive astrocytes in human post-mortem brain tissue from AD, PD, ALS, multiple sclerosis (MS), and Huntington disease (HD)." (PMID 35370777, 2022).
Infertility (8 papers, 2013 to 2023). "A previous study revealed that elevated serum IgA subclass anti-β2-GPI antibodies and immune complexes of β2-GPI strongly correlated with decreased serum C3 and C4 levels in infertile patients." (PMID 37711763, 2023). "Csmd1-knockout males show increased rates of infertility with significantly increased complement C3 protein deposition in the testes, accompanied by severe histological degeneration." (PMID 31604923, 2019). "Therefore, analysis of PST and active c3 in the sperm of patients undergoing infertility treatment should be recommended." (PMID 26791536, 2016). "A total of 116 male patients treated with their partners for infertility underwent basic semen analysis and an assessment of the presence of PST and the active c3 in sperm using flow cytometry." (PMID 26791536, 2016).
liver disease (8 papers, 2014 to 2023). "Indeed, liver disease is associated with hypocomplementemia: it is due to decreased C3 and C4 synthesis in fulminant hepatic failure, whilst in chronic active hepatitis it results from the formation of immune complexes and consequent complement activation." (PMID 32664348, 2020). "Analogous to what has been described in other liver disorders, we observed C3 deposits in the liver of NPC mice." (PMID 32244854, 2020). "In this study, the C3 level of patients with subacute liver failure was lower than that of the other three groups, and the C3 level of AIH patients was lower than that of patients with other liver diseases." (PMID 36795333, 2023).
lung disease (8 papers, 2017 to 2024). "Other studies have shown a correlation between low C3 and C4 levels and more severe forms of the disease, with extraglandular manifestations (including lung disease)." (PMID 39677201, 2024). "Patients with lung disease more frequently exhibited low C3 and C4 levels both at diagnosis and during follow-up." (PMID 39677201, 2024). "The early difference in the course of the lung disease of WT and C3+/− mice and the kinetics from day 5 on point to changes of the early, innate immune response, when C3 is only reduced, but not absent." (PMID 33767691, 2021). "C3 knockout mice infected with SARS-CoV had less lung disease than wild-type mice, suggesting that complement may play a role in coronavirus pathogenesis." (PMID 32405877, 2020). "Combined, these data demonstrate that the absence of complement provides significant improvements in pulmonary disease following SARS-CoV MA15 infection and suggest that a nonpulmonary cause might also contribute to the lack of weight loss in C3–/– mice." (PMID 30301856, 2018).
mastitis (8 papers, 2016 to 2025). Inflammation of breast tissue during lactation or postpartum due to an obstructed duct or infection. "A study of bovine mammary glands naturally infected with Staphylococcus aureus showed that the protein expression of complement component 3 (C3) and the complement and coagulation cascades pathway were significantly downregulated in the mastitis group." (PMID 35890330, 2022). "C3 is recognized as a key molecule of the complement system that regulates host defence against pathogens during mastitis." (PMID 31417691, 2019). "Western blot analysis of the milk whey of sub-clinical mastitis cases (M+, M++ & M+++) identified the accumulation of C3a, an activated product of complement component-C3." (PMID 29056672, 2017). "The C3 expression levels were significantly increased in lung and mammary tissues (P<0.05), while significantly decreased in heart, spleen, liver, and kidney tissues in mastitis cows compared with those in healthy animals (P<0.01), respectively." (PMID 35771868, 2022). "Furthermore, complement hemolytic activity and C3 concentration in milk are higher in mammary gland with mastitis than in healthy mammary gland." (PMID 35771868, 2022). "Proteins that stand out as logical candidates for further analyses include various APPs and vascular-derived proteins such as C3, C4, TF, ALB, TTR, FGA, and ITIH4 in mastitis whey of E. coli infected cows by 2-DE and label-free methods, respectively." (PMID 36335251, 2022).
metastatic disease (8 papers, 2014 to 2025). "Nsingwane and collaborators, found that C3 plasma levels were decreased in locally advanced and metastatic disease compared to resectable cancer, suggesting a loss of innate immune response." (PMID 37628784, 2023). "Similarly, C3-targeted therapeutics (both C3 convertase inhibitors and C3a antagonists) are specifically attractive for metastatic disease given the role of C3 in driving edema after radiation, which is routinely used for these tumors, as well as the role of C3 in leptomeningeal spread." (PMID 34671342, 2021).
myositis (8 papers, 2011 to 2023). "Complement C4 or C3 protein or C4P/G, HLA-DRB1*03 and/or HLA-DRB1*15, C4A deficiency or C4A GCN range of variations were risk factors for various myositis-related autoantibodies except for MSA in general." (PMID 36171069, 2023). "Following the onset of inflammatory cell infiltration, wild type mice develop severe destructive myositis, which is a major aspect of virus-induced disease in this mouse model, and we have previously shown that muscle cell killing and disease is dependent upon both C3 activation and CR3." (PMID 22457620, 2012). "Serology showed ANA 1/160–1/640 (speckled, nucleolar staining) with positive anti-PM/Scl 75 and weak anti-PM/Scl-100, but negative ENA, RF and myositis-specific antibodies and normal complement C3 and C4." (PMID 35006287, 2022). "Additionally, although not statistically significant, myositis patients were less likely to have hypocomplementemia (low C3, C4 or CH50) which correlates with the finding that they were also less likely to have renal involvement." (PMID 21827646, 2011).
pemphigus (8 papers, 2008 to 2025). Pemphigus is a group of rare autoimmune diseases that cause blistering of the skin and mucous membranes (mouth, nose, throat, eyes, and genitals).This conditioncan occur at any age, but often strikes people in middle or older age. "The distinct immunoglobulin deposition patterns, intercellular immunoglobulin G (IgG) and C3 in pemphigus variants, and linear IgG and C3 along the basement membrane in BP enabled accurate classification." (PMID 40546482, 2025). "In contrast, acantholysis in pemphigus appears to develop independently of complement activation although staining of C3 in the epithelium/epidermis is a diagnostic hall mark." (PMID 33505392, 2020). "Thus, levels of deposited C3 in SABDs and IgG1 in pemphigus seemed to differ based on the examined polymorphisms." (PMID 32235430, 2020). "Direct immunofluorescence in patients with all types of pemphigus produces a characteristic, sharp, “chicken-wire” pattern with IgG and/or C3 conjugates, localising to epithelial cell membranes." (PMID 38074463, 2023). "Third, in DIF studies, the positive rates of deposition of IgG, IgA, and C3 in intercellular space of the epidermis are very high in IgG/IgA pemphigus." (PMID 35625932, 2022). "The CA genotype (composed of allele C and A) of rs396991 in CD16A had a higher affinity for tissue-bound IgG1 in pemphigus and for C3 in subepithelial ABDs, showing statistical significance." (PMID 32235430, 2020). "Only two relations between rs396991 of CD16A (CA in SABDs and AA in pemphigus) and tissue-bound antibodies (IgG1, C3) with statistical significance were found." (PMID 32235430, 2020). "In experimental models, it was also demonstratedthat IL-1α and TNF-α were able to activate C3 mRNA in keratinocytes cultureafter stimulation with pemphigus antibodies obtained from PV patients." (PMID 18584045, 2008). "In PE, IgG/IgM and/or complement (C3) deposits are located not only in the intercellular spaces of the epidermis (typical for pemphigus) but also there are granular deposits of IgG or IgM and/or C3 along the dermal–epidermal junction (typical for lupus erythematosus)." (PMID 39860415, 2025). "Direct immunofluorescence (DIF), demonstrating intercellular deposition of IgG and C3, and indirect immunofluorescence microscopy for detecting serum autoantibodies against DSGs are highly sensitive and specific methods for diagnosing pemphigus, as aided us significantly for the patient." (PMID 36751324, 2023).
Pleural effusion (8 papers, 2022 to 2025). The presence of an excessive amount of fluid in the pleural cavity. "In our study, using multivariate logistic regression, VEGF [odds ratio (OR): 2.46, P = 0.01], TNF-α (OR: 3.64, P = 0.04), and C3 (OR: 3.77, P = 0.02) levels were identified as the independent risk factors for pleural effusions." (PMID 37993859, 2023). "While clinical findings such as low C3, anti-SS A, and anti-SM positivity, and pleural effusion were suggestive of SLE diagnosis, this was excluded because the patient did not fulfill the EULAR/ACR diagnostic criteria." (PMID 38137932, 2023). "The combination of antinuclear antibodies (ANA) positivity (titer ≥ 1:80) and decreased C3 and C4 levels in pleural effusions demonstrated a sensitivity of 82%, specificity of 89%, and a negative predictive value of 93% for distinguishing lupus pleuritis from non-lupus exudative pleural effusion." (PMID 40170018, 2025). "Elevated levels of C3 in cerebrospinal fluid are useful in diagnosing neuropsychiatric SLE and decreased levels of C3 and C4 in pleural fluid are useful in discriminating lupus pleuritis from pleural effusion of other etiologies." (PMID 36830735, 2023).
xerophthalmia (8 papers, 2012 to 2023). "The authors documented an improvement in xerophthalmia as well in some laboratory parameters (reduction of gamma globulins and IgM-RF titre, increase of C3 and C4 complement levels and white blood cell count)." (PMID 25383230, 2012). "The presence of xerophthalmia, anti-SSA and rheumatoid factor positivity, low C3 levels and other features have all shown either positive or inverse associations with the development of renal complications." (PMID 33042142, 2020). "In summary, in SLE patients with negative anti-SSA/SSB, dry eye severity was strongly correlated with anti-dsDNA and C3 but not with C4, ESR, and ANA." (PMID 27428227, 2016).
Abdominal obesity (7 papers, 2012 to 2022). Excessive fat around the stomach and abdomen. "By highlighting the associations of both complement C3 and cardiac structure with centenarian status, our study suggests that preventing abdominal obesity represents a key strategy to promote successful aging." (PMID 33221761, 2020). "Abdominal obesity was significantly associated with immunoglobulin E and complement C3 levels (P < 0.05 for all)." (PMID 30454064, 2018). "Moreover, the present study illustrates that abdominal obesity is a characteristic element of MetS associated with complement C3 levels in Chinese centenarians." (PMID 30454064, 2018). "As the first study in the world, the present study demonstrates that MetS has significant associations with immunoglobulin E and complement C3 levels, and abdominal obesity is significantly associated with immunoglobulin E and complement C3 levels in Chinese centenarians." (PMID 30454064, 2018). "The present study provides epidemiological evidence that MetS has significant associations with immunoglobulin E and complement C3 levels, and demonstrates that abdominal obesity is significantly associated with immunoglobulin E and complement C3 levels in Chinese centenarians." (PMID 30454064, 2018). "Moreover, the present study demonstrates that abdominal obesity is significantly associated with immunoglobulin E and complement C3 levels in Chinese centenarians." (PMID 30454064, 2018). "Abdominal obesity was significantly associated with immunoglobulin E [crude OR (95% CI) 0.987 (0.976–0.997); adjusted OR (95% CI) 0.987 (0.977–0.998); P < 0.05 for all] and complement C3 levels [crude OR (95% CI) 1.018 (1.011–1.026); adjusted OR (95% CI) 1.018 (1.010–1.025); P < 0.05 for all]." (PMID 30454064, 2018). "C3 and C4 are associated with daily physical activities in centenarians, and abdominal obesity in centenarians was strongly correlated with complement C3 levels." (PMID 35955822, 2022). "Since ASP is a potent stimulator of lipogenesis in adipocytes, increased complement C3 levels have the potential to disturb lipid metabolism and aggravate abdominal obesity." (PMID 33221761, 2020). "Central obesity in particular seems to trigger C3 production." (PMID 21822486, 2012). "Thus, complement C3 may aggravate abdominal obesity and affect lipid metabolism, further contributing to the development of MetS." (PMID 30454064, 2018).
amyotrophic lateral sclerosis (7 papers, 2022 to 2026). Amyotrophic lateral sclerosis (ALS) is a neurodegenerative disease characterized by progressive muscular paralysis reflecting degeneration of motor neurons in the primary motor cortex, corticospinal tracts, brainstem and spinal cord. "Blood neurofilament light chain, creatine kinase, serum ferritin, C3 and cerebrospinal fluid neurofilament light chain and chitotriosidase 1 were all significantly elevated in amyotrophic lateral sclerosis patients." (PMID 35224491, 2022). "Previously published studies have reported complement component 3 (C3) in a specific subtype of reactive astrocytes that respond to inflammation and mediate microglia–astrocyte crosstalk in a range of neurodegenerative diseases such as AD, HD, MS, and amyotrophic lateral sclerosis (ALS)." (PMID 37189441, 2023).
encephalitis (7 papers, 2017 to 2025). An acute inflammatory process affecting the brain parenchyma. "The direct cytotoxicity of complement activation has been demonstrated in patients with GAD-Ab-associated encephalitis, who exhibited increased transcriptional levels of complement protein genes (C3, C4A, C4B) and elevated levels of activated complement proteins in the CSF." (PMID 41041342, 2025). "In addition, in viral encephalitis mediated memory impairment, C1qa was upregulated, and mice deficient in either C3 or C3a receptor had reduced synaptic terminal loss." (PMID 28715462, 2017). "In summary, an early elevation of complement factors of all pathways as well as an increase of cleaved factors indicating active C3 and C5 convertases was observed in the first available CSF samples of patients with BoDV-1 encephalitis." (PMID 38591239, 2024). "Serum exosomal miR-140-5p combined with serum C3 would be a promising marker in the differential diagnosis of anti-NMDAR encephalitis with VE." (PMID 35273615, 2022). "C3-dependent viral clearance in the periphery is critical for the protection against VEEV-induced encephalitis." (PMID 34408631, 2021). "C3-dependent viral clearance in the periphery is protective against VEEV-induced encephalitis." (PMID 34408631, 2021). "ROC curve analysis showed the area under the curve (AUC) of serum exosomal miR-140-5p and serum C3 was 0.748 (76.67% sensitivity and 73.33% specificity) and 0.724 (76.67% sensitivity and 60% specificity) to distinguish anti-NMDAR encephalitis from VE, respectively." (PMID 35273615, 2022).
eosinophilia (7 papers, 2010 to 2023). "Accordingly, high levels of circulating immune complexes are detectable after 10–12 days and low levels of C4 and C3 on the 10th day, while C3a anaphylatoxin is elevated, accompanied by leukocytosis and sometimes eosinophilia, hematuria, and proteinuria." (PMID 36936215, 2023).